IL10 (interleukin 10)
Diseases named in the same sentence as IL10 in open-access papers (continued):
Sharing a sentence is not in itself a finding about the gene and the disease.
COVID-19 (continued). "Levels of pro-inflammatory (IFN-γ, IL-1β, IL-6, IL-9, IL-12p70, CCL11) and anti-inflammatory (IL-4, IL-5, IL-10, IL-13) cytokines, as well as VEGF, were higher in severely ill COVID-19 patients as compared to pandemic influenza A(H1N1) subjects." (PMID 33995342, 2021). "It is known that in severe cases of COVID-19, patients showed increased serum cytokine levels of IL-2, TNFα, IL-1β, IFNγ, MCP-1, MIP1α, IL-10, and IL-6." (PMID 34244584, 2021). "Early studies have demonstrated that asymptomatic or mild COVID-19 cases with immune skewing towards a systemic TH2 characterized by increases in IL-4 and IL-10." (PMID 34265022, 2021). "Thus, IL-10 appears to be a key cytokine in the inflammatory process related to COVID-19 and to correlate IL-10 levels with other inflammatory parameters may contribute to the understanding of how this cytokine storm can lead to damage in other organs, like the liver." (PMID 34336904, 2021). "Acute COVID-19 monocytes transcriptome showed upregulation of anti-inflammatory tissue repair genes such as BCL6, AREG and IL-10 and increased accessibility of chromatin." (PMID 34572439, 2021). "Our study demonstrates that the levels of IL-6, IL-8, IL-10, VEGF, MCP-1 and EGF were significantly increased in the severe COVID-19 patients." (PMID 34868558, 2021). "In COVID-19 related cytokine storm syndrome (COVID-CSS), different inflammatory cytokines such as Interleukin-1 (IL-1), Interleukin-10 (IL-10), and tumor necrosis factor (TNF)-α are elevated about 2-100 fold above normative values." (PMID 35155571, 2021). "Previous studies have found an association between an increase in levels of IL-2, IL-6, IL-7, IL-10 and TNF-α and the severity or mortality of COVID-19." (PMID 34490065, 2021). "Several pro-inflammatory cytokines including IL10, MCP1, TNFa, MDC, GRO, sCD40L, IL1Ra and IP10 were higher after COVID-19 compared to controls consistent with findings from several recent studies." (PMID 34838058, 2021). "It was reported that plasma cytokines IFN-γ, IL-10, IL-12p70, IL17A, IL-6 and TNF-α levels are increased in COVID-19 patients admitted to the ICU when compared with healthy controls." (PMID 34289718, 2021). "During the period of COVID-19, HLJDD was also found to play a therapeutic role in COVID-19 through regulating multiple signaling pathways based on targeting genes such as IL6, IL10, MMP9, NOS2, VEGF, and TGFβ1." (PMID 35127697, 2021). "Ferritin, D-dimer, CRP, NLR, cytokine (IL-18 and IL-10), and cytokine receptor (IL-6, IL1-Ra, and sCD25) test results combined with clinical data can contribute to the early identification of critical COVID-19 patients." (PMID 34422145, 2021). "Multiple studies have also demonstrated elevation of additional inflammatory markers such as IL-6, IL-8, IL-10, and TNF-α in COVID-19 patients." (PMID 33996864, 2021). "Significantly higher levels of galectin-3, galectin-9, IL-1β, IL-1Ra, IL-10, IFN-α2, IL-6, IL-18, and TNF-α were observed in severe COVID-19 and active AOSD patients compared with HC (all p<0.001)." (PMID 34367188, 2021). "Several cytokines including interleukin (IL)-6, IL-10, interferon-γ (IFN-γ), and tumor necrosis factor-α (TNF-α) have been observed to increase dramatically during acute infection in COVID-19 patients." (PMID 34307393, 2021). "Levels of IL-6, IL-10, IL-15, IFN-γ, TNF-α, CCL2, CCL3, CCL4, CCL26, CXCL9 and CXCL10 were significantly elevated both in COVID-19 critical clinical condition and in MAS patients as compared to healthy controls." (PMID 34226537, 2021). "High levels of IL (Interleukin) -6 and IL-10, while low levels of CD4+ T and CD8+ T cells can be observed in COVID-19 patients." (PMID 34054522, 2021). "MDSC display abundant immune suppressive mechanisms including IL-10, TGF-β, Arg-1, IDO-1, ILT3, COX-2, PD1L, and others, all of which were clearly increased in COVID-19 patients in this study." (PMID 33692788, 2021). "However, it is unclear how IL-10 could be correlated to the severity of COVID-19." (PMID 34046036, 2021).
COVID-19 (continued). "Increased cytokine secretion, including IL-2, IL-4, IL-6, IL-10, tumor necrosis factor (TNF)-α, and IFN-γ, in COVID-19 patients has been reported." (PMID 33445583, 2021). "Among the upregulated genes in post-COVID-19 monocytes, we still found the acute-COVID-19 upregulated BCL6, AREG and IL-10." (PMID 34572439, 2021). "In this study, we investigated the effect of pre-analytical sample handling variations on levels of COVID-19-relevant cytokines IFN-γ, IL-10, IL-12p70, IL-17A, IL-6 and TNF-α." (PMID 34289718, 2021). "Overall, our study showed that high levels of immune-inflammatory markers (IL-6, IL-8, IL-10 and TNF-a) were all strong predictors of severe COVID-19 by ROC analysis." (PMID 34488665, 2021). "The transplanted MSCs significantly elevated IL-10 and reduced TNF-α concentrations in seven MSC transplanted patients with COVID-19-pneumonia compared to the three patients in the placebo control group receiving standard care." (PMID 33363221, 2020). "Results showed that COVID-19 patients have higher serum level of cytokines (TNF-α, IFN-γ, IL-2, IL-4, IL-6 and IL-10) and CRP than control individuals." (PMID 32475230, 2020). "A study found an increase in Th17 cell and inflammatory cytokines (IL2, IL6, IL10, and IFN-γ) in severe COVID-19 patients compared to mild cases." (PMID 33362771, 2020). "In early studies, COVID-19 was also reported to induce increased secretion of T-helper-2 (Th2) cytokines (e.g., IL4 and IL10) that suppress inflammation." (PMID 32393351, 2020). "Higher levels of IL-6 and IL-10 as well as lower levels of CD4+ and CD8+ T cells found in COVID-19 patients correlated with the severity of the disease." (PMID 32944387, 2020). "The comparison of cytokine concentrations in supernatants of PBMCs from COVID-19 patients vs. healthy subjects revealed lower concentrations of IL-10 and higher concentrations of IL-18 in supernatants of CD3/CD28-activated PBMCs from COVID-19 patients." (PMID 33634100, 2020). "Significantly high blood levels of cytokines and chemokines were detected in patients with severe cases of COVID-19 admitted to the intensive care unit, including IL2, IL7, IL10, GCSF, IP10, MCP1, MIP1α, and TNFα which are believed to promote disease severity." (PMID 33041985, 2020). "We used a multiplex cytokine assay to measure serum IL-6, IL-8, TNF, IL-1β, GM-CSF, IL-10, IL-33 and IFN-γ in 100 hospitalised patients with confirmed COVID-19 at admission to University Hospital Southampton (UK)." (PMID 32962703, 2020). "At the same time, T cell counts recovered was related to the concentration of cytokines in plasma likes IL-6, IL-10, and TNF-α, which was decreased in the disease resolution stage of COVID-19 patients." (PMID 33261583, 2020). "Intriguingly, severe COVID-19 patients show elevated levels of serum cytokines such as IL-6, TNF-α, and IL-10, and also increased sCD25 in the serum." (PMID 33178221, 2020). "We also discovered there were higher levels and proportion of the elevation of LDH, IL-2R, IL-6, IL-8, IL-10 and TNF-α, furthermore, there were only higher levels of CRP and ferritin in the critically ill COVID-19 patients." (PMID 32788884, 2020). "Furthermore, after ssRNA and R848 stimulation, patients’ PBMCs released high amounts of IL-10, a predominantly anti-inflammatory/pro-tolerogenic cytokine, implying that PBMCs might be a prolific source of IL-10, which is also elevated in the sera of COVID-19 patients." (PMID 33003471, 2020). "Visceral adipose tissue-resident Tregs of lean individuals produce high levels of anti-inflammatory IL-10, which upregulates Th2 pathways, antagonizing effects of IL-6 and TNF, a mechanism also supposed to occur in COVID-19 patients." (PMID 33510644, 2020). "A comparison performed with 40 patients showed an increase of IL-2, IL-6, IL-10, and IFN-γ in the serum of 13 patients with the severe form of COVID-19 compared to 27 cases of mild disease." (PMID 33584667, 2020).
COVID-19 (continued). "A previous study demonstrated the changes in the levels of inflammatory cytokines, such as IL-2, IL-7, IL-10, and tumor necrosis factor (TNF)-α, in the serum of COVID-19 patients." (PMID 32484453, 2020). "In COVID-19, a significant elevation of cytokines (interferon [IFN]-γ, tumor necrosis factor [TNF]-α, interleukin [IL]-6, IL-10, IL-2, IL-1, and others) and lymphocytopenia are found." (PMID 32510901, 2020). "A study that evaluated eight critically ill Chinese pediatric COVID-19 patients treated in the ICU, with ages ranging from 2 months to 15 years, reported increased levels of IL-6, IL-10, and IFN-γ among other laboratory findings." (PMID 32612617, 2020). "Of the 13 mediators analyzed in serum IL-6, IL-10, monocyte-chemoattractant protein-1 (MCP-1) and interferon gamma-induced protein 10 (IP-10) were significantly increased in COVID-19 patients and tracked with disease severity." (PMID 32943497, 2020). "In COVID-19 patients, the numbers of CD4+ and CD8+ T cells decreased, while the levels of IL-6 and IL-10 increased in severe cases." (PMID 33028689, 2020). "In COVID-19, a sustained decrease in CD4+ and CD8+ T cells, especially CD8+ T cells, is observed, despite an increase in IL-6, IL-10, IL-2, IFN-γ levels, and neutrophil counts." (PMID 33335532, 2020). "While the elevation of CXCL10, IL-10, CCL2, IL-6 has been extensively documented in severe COVID-19, our work demonstrates a clear correlation between these cytokines and plasma viral load." (PMID 33317616, 2020). "During early disease, patients who proceeded to develop COVID-19 severe pneumonia (SP) and DHF had significantly higher levels of IL-6, IL-10 and MIP3α than those who developed mild illness." (PMID 33199778, 2020). "There are higher levels of inflammatory factors, including IL-2, IL-4, IL-6, IL-10, TNF-α, and IFN-γ, found in COVID-19 patients than in healthy people." (PMID 32985562, 2020). "In the two cases of severe COVID-19, the levels of CRP, PCT, serum ferritin, IL-6, and IL-10 were significantly increased, whereas the numbers of CD3+, CD4+, CD8+ T lymphocytes, and CD16 + CD56 natural killer cells were decreased." (PMID 32574284, 2020). "It was first reported that several pro-inflammatory cytokines and chemokines, including IL-2, IL-7, IL-10, CXCL10 (IP-10), CXCL8, CCL2 (MCP1), TNFα, and IFNγ were higher in the plasma of COVID-19 patients as compared to healthy controls." (PMID 33363221, 2020). "An elevation of serum levels of several cytokines such as interleukin (IL)-6, IL-10, and IFN-γ is reported in critically ill COVID-19 patients." (PMID 33203860, 2020). "Significantly up-regulated levels of cytokines and chemokines including IL1-β, IL1RA, IL10, IL9, IL8, IL7, basic FGF2, GCSF, GMCSF, IFNγ, IP10, MCP1, MIP1α, MIP1β, PDGFB, TNFα, and VEGFA in blood, have been confirmed in COVID-19 patients." (PMID 33041797, 2020). "Some of these proinflammatory cytokines, including IL-2, IL-7, IL-10, G-CSF, IP-10, MCP-1, MIP-1a, and TNF-α, are highly elevated in the blood of severely ill COVID-19 patients." (PMID 33101440, 2020). "In our study, cytokines including IL-1β, IL-6, IL-10, and TNF-α were elevated in severe COVID-19 and active AOSD, compared with healthy controls, indicating the potential contribution of cytokine storm in pathogenesis of COVID-19 and AOSD." (PMID 33552062, 2020). "According to a recent report analyzing 138 hospitalized patients with COVID-19 high plasma concentrations of cytokines and chemokines including IL-2, IL-7, IL-10, G-CSF, IP-10, MCP-1, MIP-1A, and TNF-α were observed in the COVID-19 severe cases." (PMID 33154753, 2020). "In conclusion, our findings suggest that both COVID-19 and AOSD have elevated level of ferritin and cytokines, including IL-1β, IL-6, IL-10, IL-18, and TNF-α, indicating systemic inflammation in the pathogenesis of COVID-19 and AOSD." (PMID 33552062, 2020).
COVID-19 (continued). "In this context, we herein demonstrate that mononuclear cells, which were isolated from subjects following severe COVID-19, had higher mRNA expression levels of cytokines such as TNF and IL10, as compared to individuals with milder disease." (PMID 33087116, 2020). "In both analyses, COVID-19 patients with organ failure showed significantly higher IL-6 and IL-10 levels than those without organ failure, with greater variability in IL-10 findings (I2 = 86%, P = 0.0006)." (PMID 41585373, 2025). "Conversely, anxiety may impact the function of five COVID-19 regulators, including the activation of four proteins (IL6, angiotensin 2, TNF, and IL10) and the inhibition of one protein (DPP4)." (PMID 40766923, 2025). "Our results show that combined high levels of IL-6 and IL-10 in patients with pneumonia can have a significant impact on clinical practice by differentiating between COVID-19 and non-COVID-19 pneumonia." (PMID 40508859, 2025). "From a host genetic perspective, elevated levels of IL-6, IL-10, IL-13, MMP-7, ferritin, and D-dimer were observed in COVID-19 patients across all genotypes, with the CC genotype associated with the highest concentrations, suggesting a heightened inflammatory and pro-thrombotic state." (PMID 40733568, 2025). "Critically ill COVID-19 patients frequently exhibit a cytokine storm, characterized by elevated levels of cytokines such as IL-6, IL-8, IL-12, TNFα, IL-17, MCP-1, IP-10, and IL-10." (PMID 40160814, 2025). "Meta-analyses of IL-6 and IL-10 levels in COVID-19 patients with and without organ failure provide insights into the differences between these two groups." (PMID 41585373, 2025). "In contrast, the levels of TNF-α and IL-10 were not significantly different between the severe and non-severe COVID-19 groups." (PMID 39859379, 2025). "The subsequent RuxCoFlam trial included COVID-19 patients with the same CIS cut-off (≥10) and yielded a similar response rate (71%), which was accompanied by a significant reduction of inflammation markers such as IFN-γ, IL-6, and IL-10 (p < 0.001 each)." (PMID 40430208, 2025). "Furthermore, IL-10 has the potential to predict the depression of PaO2/FiO2 and the severity of ARDS in COVID-19." (PMID 40761632, 2025). "To gain a comprehensive understanding of the demographic factors and laboratory biomarkers’ impact on ARDS in COVID-19, we conducted a correlation analysis between age, BMI, CRP, hematological biomarkers (neutrophil, lymphocyte, and NLR), and cytokines (IL-10 and TNF-α), with PaO2/FiO2." (PMID 40761632, 2025). "At moderate exposure level, the COVID-19-positive individual exhibited higher cytokine peaks following the heterologous booster, whereas the COVID-19-negative individuals showed attenuated responses for IFN-γ, TNF, and IL-10." (PMID 40406109, 2025). "Our results associating IL-10 with lower COVID-19 severity suggest elevated IL-10 might suppress cytokine storms, protecting SLE patients – a compensatory mechanism also proposed in COVID-19." (PMID 40643149, 2025). "Moderate and severe COVID-19 patients but not critical COVID-19 patients showed higher levels of IL-10 compared to non-COVID-19 patients." (PMID 40508859, 2025). "Previous studies reported increased levels of IL-10, IL-6, and TNF-α in severe COVID-19 patients." (PMID 39856771, 2025). ", suggesting that the differences in IL-10 levels between our studies were not due to COVID-19 versus non-COVID ARDS." (PMID 41339723, 2025). "Our findings agree with a recent meta-analysis including non-severe and severe COVID-19 patients, suggesting that IL-10 precisely predicted disease severity and mortality." (PMID 40143288, 2025). "The evaluation of plasma levels of TNF-α, IFN-γ, and IL-10 showed that although IFN-γ levels were higher in individuals with the severe form of COVID-19 in the bivariate analysis, this result was not confirmed in the multiple logistic regression analysis." (PMID 39859379, 2025).
COVID-19 (continued). "Residents of EA with COVID-19 and FLS had higher production of IL-12p70, IL-6, IL-1β, IL-2, and IL-1ra compared to residents of NEA, as well as an increased production of IL-10 in COVID-19 patients." (PMID 40165959, 2025). "Similarly, regarding inflammatory cytokines, high levels of several cytokines, such as IL-1β, IL-2, IL-6, IL-7, IL-8, IL-10, CXCL10/IP-10, MCP-1, and TNF-α have already been described according to the severity of COVID-19." (PMID 39861879, 2025). "In pregnant women with acute COVID-19, a significant positive correlation between APTT, TT and a large subset of the tested inflammatory cytokines/chemokines was observed, including IL-6, INF-α2, MCP-1, IL-10, and IL-18." (PMID 40303405, 2025). "Notably, convalescent serum showed significant decreases in sICAM-1, sVCAM-1, P-selectin, IL-1α, IL-1ra, IL-10, IL-27, TNF-α, TGF-α, and G-CSF compared to serum from severe COVID-19 patients." (PMID 41583455, 2025). "We observed higher levels of bilirubin, D-dimer, C-reactive protein, urea, and plasmatic cytokines, such as IL-1β, IL-6, IL-8, IL-10, IL-17A, IL-23, TNF-α, and IFN-α in individuals with the critical form of acute COVID-19 compared to individuals with the severe and/or moderate WHO clinical forms." (PMID 39861879, 2025). "Importantly, elucidation of putative serum mediators revealed a significant upregulation of key cytokines in COVID-19 positive patients compared to controls, including IL-6, TNF-α, IL-1β, IL-10, and CRP." (PMID 38041432, 2024). "COVID-19 patients with CVD who were taking statins had significantly lower median concentrations of IL-6 (21 vs. 44 pg/mL, p = 0.027), TNFα (21 vs. 39.5 pg/mL, p = 0.036), and IL-10 (19 vs. 25.5 pg/mL, p = 0.025) compared to COVID-19 patients with no CVD." (PMID 39518552, 2024). "Another study observed a similar rise in the Th17/Treg ratio in PBMCs from patients with COVID-19, associated with negative outcomes and lower levels of TGF-β and IL-10." (PMID 39519310, 2024). "The authors also investigated Th1 and Th2 cytokine dynamics in COVID-19 patients, and found that stable ratios of Th2 cytokines (IL-4, IL-6, IL-10) to IFN-γ over time indicate a dysregulated immune response, which is critical in understanding COVID-19 pathophysiology." (PMID 39518964, 2024). "For this purpose we relied on the Comparative Toxicogenomic Database (CTD), GeneMANIA, and ToppGene Suite portal and identified a set of five common genes (IL1B, CXCL8, IL6, IL10, TNF) for the six metals and COVID-19, all of which code for pro-inflammatory and anti-inflammatory cytokines." (PMID 38963144, 2024). "Plasma levels of IL-2, IL-7, IL-10, granulocyte colony-stimulating factor (G-CSF), IP-10, MCP1, macrophage inflammatory protein 1α (MIP1α), and tumor necrosis factor (TNF) have been observed in patients with severe COVID-19 were higher than in healthy adults." (PMID 38648205, 2024). "Although IL-10 and IL-6 were not correlated within the group of patients with severe COVID-19, they were directly proportional in deceased and non-severe groups." (PMID 39633683, 2024). "Patients with severe COVID-19 who did not survive the disease have higher levels of IL-10 compared to surviving patients." (PMID 39281667, 2024). "In addition, CCL2 expression exhibited higher levels in classical monocytes and dendritic cells, while an upregulation of IL10 mRNA was detected in monocytes and CD4+ T cells of COVID-19 patients." (PMID 39625479, 2024). "It has been shown that some parameters related to inflammation, such as TNFα, IL-6, interleukin-8 (IL-8), interleukin-10 (IL-10), CRP, white blood cell count (WBC), lymphocyte count (LC), and the number of neutrophils (NC) are correlated with the severity of COVID-19." (PMID 39335569, 2024).